FASN (fatty acid synthase)
Diseases named in the same sentence as FASN in open-access papers (continued):
Sharing a sentence is not in itself a finding about the gene and the disease.
infection (continued). "In terms of fatty acid biosynthesis, we found that expression of the key protein fatty acid synthase (FASN) was 10-fold higher after CH60 infection, potentially stimulating fatty acid synthesis." (PMID 30197639, 2018). "We note however that the knockdown of FASN was very transient which suggests that there is a high level of transcription of this gene, even under conditions of infection." (PMID 28193229, 2017). "This would suggest that knock down of FASN before infection results in a cellular environment unsuited to the establishment of infection, possibly by altering endosomal trafficking or another process required to establish the infection." (PMID 28193229, 2017). "Dengue virus (DENV) infection redistributes fatty acid synthase to viral replication sites through interaction between non-structural protein 3 (NS3) and fatty acid synthase in order to promote cellular fatty acid synthesis." (PMID 28496435, 2017). "Three days post infection, we determined endogenous FASN expression of these cells by Western blot analyses." (PMID 27713175, 2016). "Treatment with cerulenin and C75, two inhibitors of fatty acid synthases (FASN), drastically reduced the cellular infection of both DENV and WNV, in vitro." (PMID 24517970, 2014). "Infection is characterized by virally-induced increases in cellular fatty acid synthesis and a redistribution of the enzyme fatty acid synthase to sites of DENV replication." (PMID 22532801, 2012). "Regarding FASN levels, they were not substantially altered by WNV infection when analyzed by western blot, consistent with that reported for DENV and in contrast to HCV-infection, which curses with an increase in FASN expression." (PMID 21949814, 2011). "Mayaro virus (MAYV) infection is inhibited by cerulenin and orlistat treatment, indicating that FASN is a host dependency factor for at least two alphaviruses." (PMID 40558086, 2025). "DENV-2 replication was reduced by the treatment of cells with FASN-specific siRNA, cerulenin, or C75, and Orlistat treatment significantly reduced infection and virion production of a lab-adapted DENV-4 strain and clinical hemorrhagic fever DENV-4 isolate (13, –, 15)." (PMID 40558086, 2025). "With regards to lipid biogenesis, exogenously expressed DENV NS3 was shown to localize with fatty acid synthase (FASN) and a de novo fatty acid biosynthesis enzyme (ACACA) and, in the context of infection, redistribute FASN to ROs to aid in their establishment and maintenance." (PMID 40005559, 2025). "FASN has been observed to have impacts on the infection of several viruses." (PMID 41196069, 2025). "Furthermore, YY1 and FASN protein levels in the livers of NAFLD mice were further increased after LV-miR-192-5p inhibitor infection." (PMID 38254634, 2023). "Alternatively, FASN inhibition during the initial infection could perturb viral replication, affecting protein composition of the virions, which then replicate less productively in naïve cells." (PMID 26659560, 2015). "Preliminary time course experiments measuring RSV A2, PIV3, and HRV16 infection daily starting at 24 hpi indicated that the effect of the FASN inhibitors was most pronounced at 72 hpi, based on which we chose 72 hpi as the most informative time point (data not shown)." (PMID 26659560, 2015). "Therefore, elucidating the mechanisms underlying FASN depletion in virus-infected cells deserves further study in the future, which would significantly contribute to our comprehensive understanding of the detailed interplay between BoAHV-1 productive infection and FASN signaling." (PMID 41196069, 2025). "Additionally, knockdown of the FASN gene suppressed the infection and replication of SGIV in vitro." (PMID 32849631, 2020). "In vitro, CVB3 upregulated FASN expression in a B-lymphocyte cell line, and in HeLa cells, FASN inhibition with cerulenin or C75 reduced CVB3 replication and production of infectious virions while delaying infection-induced cytopathic effects." (PMID 40558086, 2025).
infection (continued). "Furthermore, the observation that FASN upregulation correlates with viral load and infection kinetics—where higher MOIs lead to accelerated FASN induction—further supports the hypothesis that HSV-1 actively exploits lipid biosynthesis to support its replication cycle." (PMID 40327680, 2025). "This observed expression of FASN throughout EBV-driven B cell immortalization, combined with the observed cytotoxicity of palmitate upon dual SCD1 and FADS2 loss, led us to hypothesize that SCD1 and FADS2 prevent palmitate-induced lipotoxicity throughout infection." (PMID 40403013, 2025). "In this study, we observed that both viral acute infection and latency in bovine trigeminal ganglia (TG) neurons, as well as virus productive infection at later stages in Neuro-2A and MDBK cells, significantly reduced FASN protein levels." (PMID 41196069, 2025). "When MDBK cells were infected with BoAHV-1 at a multiplicity of infection (MOI) of 1 over various time points, FASN protein levels significantly decreased at 24 hpi, showing a reduction of approximately 30.48% compared to the mock-infected control." (PMID 41196069, 2025). "Here, our studies suggest that BoAHV-1 either acute infection in cattle trigeminal ganglia (TG) neurons or productive infection in cell cultures, including MDBK and Neuron-2A cells, leads to a unanimous decrease of FASN protein expression." (PMID 41196069, 2025). "The rearrangement of the correlation between FASN and viral proteins NS3 and NS5 of DENV, ZIKV, and JEV upon natural infection." (PMID 40131913, 2025). "To examine their roles in infection, we monitored the viral yield of CVB3-infected cells treated with inhibitors that block FASN and PLA2G4A enzymatic activities." (PMID 38953667, 2024). "Despite being important for infection, cleavage of FASN and PLA2G4A hints that lipid synthesis and membrane remodeling are regulated during infection, possibly to facilitate specific steps of the viral life cycle." (PMID 38953667, 2024). "Most candidate proteins such as PLA2G4A, FASN, HNRNPH2, and LARP4 showed detectable cleavage products at 5 h.p.i. that were stable at later times of infection." (PMID 38953667, 2024). "EBV early infection also boosts key fatty acid synthesis enzymes, ACACA and FASN, to convert acetyl-CoA derived from glycolysis into palmitate, facilitating lipogenesis." (PMID 38659762, 2024). "The infection and replication of SGIV were increased after exogenous addition of palmitic acid but suppressed after knockdown of fatty acid synthase (FASN), of which the primary function was to catalyze palmitate synthesis." (PMID 32849631, 2020). "Specifically, enzymes in the lipid biosynthesis pathway such as fatty acid synthase (FAS) are recruited to viral replication sites by interaction with viral proteins and displayed enhanced activities during infection." (PMID 30118512, 2018). "Upon infection dengue NS3 was found to interact with Rab18, which allowed recruitment of FASN to viral replication sites, thus promoting fatty acid biosynthesis to increase their local concentration." (PMID 29915602, 2018). "Interference of fatty acid synthase with either siRNA or orlistat had marked effects on virus production, with orlistat having an EC50 value of 10.07 μM at 24 h post infection." (PMID 28193229, 2017). "Despite its requirement during infection, FASN protein levels do not dramatically increase during DENV infection, perhaps because during DENV infection, FASN protein localization is manipulated by DENV non-structural protein 3 (NS3)." (PMID 40558086, 2025). "In a previous study, DENV NS3 was shown to interact with FASN and to induce the re-localization of FASN to the DENV replication complex to support viral replication although infection did not increase overall FASN expression." (PMID 40131913, 2025). "We observed colocalization between dsRNA and FASN at 24 hours post infection in DENV infection but failed to see it in ZIKV and JEV infection in a single plain analysis." (PMID 40131913, 2025).
infection (continued). "Next, to test our hypothesis regarding the impact of HSV-1 on FASN, we quantified the FASN mRNA expression levels in SH-SY5Y cells previously infected with HSV-1 at 8, 24, and 32 hours post-infection (hpi)." (PMID 40327680, 2025). "Infections with CSFV, BVDV, and HCV have been shown to enhance FASN expression (31, –, 33)." (PMID 41196069, 2025). "Recent studies demonstrated that EBV activates SREBP-dependent mevalonate and fatty acid synthesis pathways early after infection, and that LMP1 alone is sufficient to drive SREBP1/FASN activity and lipid droplet biogenesis, positioning lipogenesis as a core latency output." (PMID 41218077, 2025). "However, a shift toward increased production of fatty acid synthase (e.g., Fas2) during established bacterial coinfection may provide a window of opportunity to disarm the fungi through inhibition of these proteins and prevent an active infection within the host." (PMID 35862772, 2022). "To assess whether fatty acid synthesis is involved in SGIV replication, we focused on ACC1 and FASN, the two most crucial restriction enzymes, and explored their roles in SGIV infection by corresponding inhibitors and specific siRNA." (PMID 35215774, 2022). "The expression of lipid metabolism related enzymes ACC, FASN, PLD1, p-PLD1, and SCD1 in Ad-Vp3-infected cells were significantly higher at 12 and 24 h, and significantly lower at 36, 48, and 72 h post-infection when compared with the Ad-Mock infected cells (p < 0.05)." (PMID 33718168, 2021). "Infection with dengue virus does not affect FASN expression levels, but rather its redistribution to virus-triggered structures referred to as convoluted membranes." (PMID 29915602, 2018). "We further investigated changes in protein expression of genes involved in lipid metabolism, and levels of three proteins (ACC1, PPARγ and FASN) were determined by western blotting on days 1 to 3 post infection after infection with DENV-4LAB and DENV-4DHF or mock infection." (PMID 28193229, 2017). "Infection of WNV, and specifically viral RNA replication, were dependent on fatty acid synthesis, as revealed by the inhibitory effect of cerulenin and C75, two pharmacological inhibitors of fatty acid synthase, a key enzyme of this process." (PMID 21949814, 2011). "Both fatty acid synthase (Fas) and sterol regulatory element-binding protein 1c (Srebf1 in mice) expression levels were significantly down-regulated during long-term infection but not during short-term infection in wild-type mice." (PMID 21625524, 2011). "In addition, we sought a better understanding of ubiquitin-mediated PEPCK1 and FASN degradation by transfecting HA-tagged ubiquitin plasmids into mouse primary hepatocytes with or without Ad-TRIM21 infection." (PMID 37249651, 2023). "Under the CDRV infection, the greatest up-regulated proteins (over 5 folds) were serum amyloid protein (U3IC83) and alpha-1-acid glycoprotein (U3I466); and the greatest down-regulated proteins were malic enzyme (U3IL38), fatty acid synthase (R0KBE2), and acetoacetyl-CoA synthetase (U3IQX8)." (PMID 29973707, 2018). "We found that infection with Jad/C(4fC) resulted in the significant upregulation of c-MYC (P < 4 × 10−6), TBX3 (P < 0.0006), AXIN2 (P < 0.0068), FNDC3B (P < 1 × 10−5), FASN (P < 0.0005) and CCND1 (P < 0.0002), with c-MYC and TBX3 showing the highest upregulation levels." (PMID 30046100, 2018). "In addition, FASN inhibition reduced the levels of RSV F poly-A (message) RNA and genomic RNA 48–72 hours post infection, and of RSV F and G proteins at 24 and 30 hours post infection." (PMID 26659560, 2015). "To test whether FASN inhibition has an antiviral effect in vivo, we infected BALB/c mice with RSV A (Long) by intranasal inoculation, and orally administered 50 mg/kg TVB-3166 twice a day, starting either on the day of infection or one day post infection." (PMID 26659560, 2015).
infection (continued). "Results showed that the percentage of infection was significantly reduced in FASN siRNA treated cells as compared to siGFP or cells not treated with siRNA, and that virus titer was reduced by some 4Log10 in FASN siRNA treated cells as compared to siGFP or cells not treated with siRNA." (PMID 28193229, 2017). "Therefore, our findings support a model in which, upon infection with HIV and/or HCV, changes in circulating levels of extracellular FASN take place through molecular mechanisms likely unrelated to established pathways that regulate the intracellular FASN expression." (PMID 20707918, 2010). "Following infection with HSV-1 (MOI 1), FASN depletion had no impact on the expression of HSV-1 ICP27 and gD proteins or on intracellular and extracellular viral loads (respectively)." (PMID 40327680, 2025). "In vitro, FASN localizes to WNV replication complexes early after infection, and like DENV infection, FASN localization was not accompanied by changes in FASN protein levels." (PMID 40558086, 2025). "P3HR-1 infection failed to upregulate ACC1, FASN or EBNA2 target MYC, as did infection with UV-irradiated B95-8, which can enter cells but does not induce EBV-encoded genes." (PMID 31518366, 2019). "In addition, the expression of fatty acid synthase (FAS) in lipogenesis was downregulated, while the lipogenic gene acetyl coenzyme A carboxylase 1 (ACC1), had no obvious alteration after infection (P < 0.05)." (PMID 34552973, 2021).
metabolic disease (31 papers, 2010 to 2025). A congenital disorder (due to inherited enzyme abnormality) or acquired (due to failure of a metabolically important organ) disorder resulting from an abnormal metabolic process. "Our results confirm the key role of FASN in metabolic disease risk and provide insights into how specific genetic variants in this gene exhibit regulatory functional genomic effects that contribute to metabolic health." (PMID 35843982, 2022). "NAFLD is a major type of metabolic disorder disease that has a high risk of progression to HCC, and USP14 deubiquitinates FASN by directly interacting with it and promoting FASN stability." (PMID 37190313, 2023). "In conclusion, the results of our present study demonstrate that USP14 plays an important role in hepatosteatosis through FASN stabilization and represents a therapeutic target in fatty liver and related metabolic disorders." (PMID 30425250, 2018). "Given the developmental programming of metabolic outcomes, interventions aimed at modulating FASN activity may have long-lasting benefits in managing metabolic diseases." (PMID 40541585, 2025). "Overall, the outcome of PUFA supplementation may depend on the degree of endogenous DNL and combining PUFA supplementation and FASN inhibition might be a promising approach to target metabolic disease." (PMID 38167725, 2024). "With respect to the modulation of key molecules for metabolic diseases, such as FASN and CBP, USP14 might not only disassemble the ubiquitin chain on target proteins, but might also affect the incorporation of the targets into the proteasome." (PMID 36834633, 2023). "Several effective FASN inhibitors have been reported for potential utility in metabolic disease." (PMID 38254634, 2023). "Interestingly, many of the DEGs common in both analyses are connected to metabolic diseases and are considered potential therapeutic targets (e.g., FASN, RTN3)." (PMID 30509175, 2018). "Fatty acid synthase (FAS) levels in endothelial cells are reduced in metabolic disorders, and the absence of FAS in endothelial cells exacerbates inflammatory responses and impairs angiogenesis, the CD36 receptor play a key role in vascular injury." (PMID 40969373, 2025). "Therefore, celastrol is effective for inhibiting FASN-mediated liver steatosis in AKT/c-Met HCC mice, which is beneficial for preventing HCC, and so it might be considered as a therapeutic agent for metabolic diseases." (PMID 35539339, 2018).
neurodegenerative disease (4 papers, 2024 to 2025). A disorder of the central nervous system characterized by gradual and progressive loss of neural tissue and neurologic function. "We also plan to construct a mouse model carrying the V2005A point mutation in FASN to further investigate the role of FASN point mutations in neurodegenerative diseases." (PMID 40019378, 2025). "Additionally, investigations into the interplay between HSV-1 and host lipid metabolism in more complex in vivo models—especially those relevant to neurodegenerative diseases—will be crucial for advancing this field and assessing the translational potential of FASN inhibitors." (PMID 40327680, 2025). "Targeting proteins such as fatty acid synthase (FASN), diacylglycerol O-acyltransferase 1 (DGAT), and ATP-citrate lyase (ACLY) has shown promise in alleviating some symptoms of neurodegenerative diseases." (PMID 41373990, 2025).
adenocarcinoma (3 papers, 2012 to 2025). A common cancer characterized by the presence of malignant glandular cells.
inflammation (3 papers, 2020 to 2023). Aberrant reaction of the microcirculation characterized by movement of fluid and leukocytes from the blood into extravascular tissues. "Our findings indicate that overexpression of FASN protects against BLM-induced lung inflammation and fibrosis, and these beneficial effects are associated with stabilized mitochondrial membrane potential and reduced mitochondrial ROS production." (PMID 37270622, 2023). "Using FASN transgenic mice, we showed that FASN overexpression has a protective effect against BLM-induced lung inflammation and fibrosis." (PMID 37270622, 2023).
hematologic cancer (2 papers, 2012 to 2021). "Within hematological cancer cell lines, the coessentiality network is significantly restructured, with the ACACA/FASN module correlated with SCD in most backgrounds (r = 0.35, P < 10−18) but strongly anticorrelated in 36 blood cancer cell lines (r = −0.52, P < 10−3)." (PMID 34764293, 2021). "While the concept that FASN is a useful therapeutic target for epithelial cell malignancies is relatively supported, the role of FASN in hematologic cancer has not been extensively examined." (PMID 22485149, 2012).
hematologic malignancies (2 papers, 2012 to 2022). "Fatty acid synthase (FASN) is also upregulated in various hematological malignancies." (PMID 36106108, 2022). "Of note, the high expression level of FASN is not a universal phenomenon in hematologic malignancies." (PMID 22485149, 2012). "However, the relevance of FASN in hematologic malignancies has not been fully examined." (PMID 22485149, 2012).